LYZL6 (lysozyme like 6)
Description:
May be involved sperm-egg plasma membrane adhesion and fusion during fertilization. Exhibits bacteriolytic activity in vitro against Micrococcus luteus and Staphylococcus aureus. Shows weak bacteriolytic activity against Gram-positive bacteria at physiological pH. Bacteriolytic activity is pH-dependent, with a maximum at around pH 5.6.
Synonyms: LYC1; PRO1485; TKAL754; HEL-S-6a; LYZB; UNQ754
Tractability: Antibody: UniProt places it where antibodies can reach, with high confidence; UniProt predicts a signal peptide or a membrane-spanning region; its Gene Ontology location is reachable by antibodies, with medium confidence.
Gene: Protein-coding gene on chromosome 17 (35,934,518 to 35,943,713, reverse strand). Ensembl gene ENSG00000275722.
Subcellular location: Secreted; Cell surface; Cell projection, cilium, flagellum
Gene Ontology:
Molecular function: lysozyme activity
Biological process: defense response to bacterium; fertilization; fusion of sperm to egg plasma membrane involved in single fertilization
Cellular component: cell surface; extracellular region; sperm plasma membrane; acrosomal vesicle; sperm flagellum; sperm midpiece; motile cilium
Genetic constraint (gnomAD): Loss-of-function variants: 27 observed, 19.83 expected, observed/expected ratio (o/e) 1.36, 90% interval 1 to 1.82. The upper end of that interval is the gene's LOEUF score, 1.82, which puts it in group 6 of 6, group 1 being the genes least tolerant of losing a copy. Missense variants: 173 observed, 189.53 expected, observed/expected ratio (o/e) 0.91, 90% interval 0.81 to 1.03. Synonymous variants: 72 observed, 70.98 expected, observed/expected ratio (o/e) 1.01, 90% interval 0.84 to 1.23.
Homologues: Orthologues: chimpanzee LYZL6 (99% identical), macaque LYZL6 (95% identical), pig LYZL6 (74% identical), guinea pig LYZL6 (74% identical), mouse Lyzl6 (71% identical), rabbit LYZL6 (71% identical), rat Lyzl6 (70% identical), Drosophila melanogaster CG8492 (43% identical), Drosophila melanogaster CG16756 (34% identical), Drosophila melanogaster CG7798 (34% identical), Drosophila melanogaster CG30062 (33% identical), Drosophila melanogaster CG11159 (31% identical), and 7 more. Paralogues in human: SPACA3 (43% identical), SPACA5 (43% identical), SPACA5B (43% identical), LYZL4 (42% identical), LYZ (40% identical), LYZL1 (38% identical), LYZL2 (38% identical), LALBA (27% identical).
Diseases named in the same sentence as LYZL6 in open-access papers:
LYZL6 is named in the same sentence as 6 diseases in open-access papers, as found by Europe PMC text mining. Sharing a sentence is not in itself a finding about the gene and the disease. The quoted sentences say what the papers report.
breast carcinoma (1 paper, 2022). "The LYZL6 gene shows a weak RT-PCR product in 25% of breast cancer (BC) patients but not in leukemia patients." (PMID 35627192, 2022).
leukemia (1 paper, 2022). A malignant (clonal) hematologic disorder, involving hematopoietic stem cells and characterized by the presence of primitive or atypical myeloid or lymphoid cells in the bone marrow and the blood. "These genes are LYZL6 in BC tissues and SCP2D1 and TKTL2 genes in the majority of leukemia tissues." (PMID 35627192, 2022).
cancer (1 paper, 2022). A tumor composed of atypical neoplastic, often pleomorphic cells that invade other tissues. "The LYZL6 gene was expressed in a CC cell line, while the SCP2D1 (C20orf79) and TEX33 (C22orf33) genes were found to be expressed in diverse types of cancer cell lines, including CC type." (PMID 35627192, 2022).
LYZL6 also shares sentences with these, for which no sentence is quoted: infection (2 papers); bacterial infections (1); Chagas disease (1).